GZMA (granzyme A)
Diseases named in the same sentence as GZMA in open-access papers (continued):
Sharing a sentence is not in itself a finding about the gene and the disease.
neuroblastoma (4 papers, 2020 to 2024). Neuroblastoma (NB) is the most common solid, extracranial childhood tumor. "In neuroblastoma, it was revealed that proteins within NK-cell-derived sEVs, such as perforin, granzyme A, granzyme B, and granulysin functioned in combination to induce cytotoxicity to CHLA255, a neuroblastoma cell line." (PMID 37762393, 2023). "expanded NK cells and isolated NK‐Exos loaded with cytotoxic proteins, including perforin, granzyme A, granzyme B, granulysin and FasL, and found that NK‐Exos triggered cytochrome C release from mitochondria and ER stress in recipient neuroblastoma (NB) cells." (PMID 37830387, 2023). "Yarmarkovich demonstrated that GZMA has a strong correlation with T-cell factors, and GZMA is very active in the neuroblastoma tumor microenvironment." (PMID 32963529, 2020).
psoriasis (4 papers, 2023 to 2025). An autoimmune condition characterized by red, well-delineated plaques with silvery scales that are usually on the extensor surfaces and scalp. "Our analysis identified CASP1, CASP5, AIM2, NOD2, GZMB, GZMA, and IL1B as key hub genes in the inflammatory pathways driving psoriasis pathogenesis." (PMID 40771724, 2025). "Correspondingly, cytotoxic mediators such as PRF1, GZMA, SRGN, and NKG7 were upregulated, paralleling signatures seen in αβ T cells in psoriasis." (PMID 41181116, 2025). "The results indicated that P. clypearia may affect the energy metabolism, cell growth and apoptosis by regulating genes such as Hspa1a, Hspa1b, mt-Nd4l, mt-Nd5, mt-Nd6, Bcl-2, Asns, Trib3, GzmA, CTSG, etc, thereby mitigating psoriasis-related inflammation." (PMID 41385507, 2025).
chromophobe renal cell carcinoma (3 papers, 2024 to 2025). Chromophobe renal cell carcinoma is a rare subtype of renal cell carcinoma, originating from the intercalating cells of the collecting ducts and macroscopically manifesting as a well-circumscribed, highly lobulated, solid tumor that is usually diagnosed at an early stage. "Tumours from patients with clear cell renal cell carcinoma (ccRCC) and chromophobe renal cell carcinoma (chR) contained an ILC1 population expressing granzyme A and were associated with better prognosis." (PMID 40899118, 2025). "Similarly, in chromophobe renal cell carcinoma (chRCC), high infiltration of granzyme A (GzmA)-expressing intraepithelial ILC1s was positively correlated with patient survival, with IL-15 promoting both their expansion and cytotoxicity." (PMID 40963622, 2025).
colon adenocarcinoma (3 papers, 2021 to 2024). "In addition, the positive correlations between ZC3H12C expression and highly connected CD8+ T genes were also visualized, including CD8A, CD8B, GZMA, GZMB, and PRF1 in colon adenocarcinoma and rectum adenocarcinoma." (PMID 38267865, 2024). "The Cancer Genome Atlas (TCGA)-colon adenocarcinoma (COAD) dataset was also analyzed to identify cytotoxic T lymphocyte (CTL) scores using a set of 5 previously reported genes (CD8A, CD8B, GZMA, GZMB, and PRF1) as a surrogate of tumor infiltrating CD8+ T cells." (PMID 38992029, 2024).
endometrial cancer (3 papers, 2020 to 2025). Primary or metastatic malignant neoplasm involving the endometrium (mucous membrane that lines the endometrial cavity). "It has been found that immune-related gene (GZMA) is high expressed in endometrial cancer at early stage and associated with prognosis, but the mechanism of tumor progression is unclear." (PMID 33384961, 2020). "Additionally, granzyme A (GZA) and B (GZB), and PD-1 expression is decreased in CD103-CD8+ T cells from endometrial carcinomas compared to adjacent non-cancerous tissue." (PMID 33968059, 2021).
leukemia (3 papers, 2012 to 2022). A malignant (clonal) hematologic disorder, involving hematopoietic stem cells and characterized by the presence of primitive or atypical myeloid or lymphoid cells in the bone marrow and the blood. "GZMA, one of the apoptotic effectors and direct transcriptional targets of glucocorticoid receptor, has been reported to mediate glucocorticoid-induced apoptosis of human leukemia cells." (PMID 22719835, 2012).
lymphoma (3 papers, 2018 to 2025). A malignant (clonal) proliferation of B- lymphocytes or T- lymphocytes which involves the lymph nodes, bone marrow and/or extranodal sites. "GZMA, granzyme A, can be expressed particularly highly in lymphoma cell lines and can elicit pyroptosis in neighboring cells." (PMID 40549805, 2025). "Consistent with our results with NALM6, we show that both lymphoma cell lines (Daudi and Raji) are sensitive to combined GZMA and GZMB inhibition, most likely attributed to their minimal Fas surface expression." (PMID 38307835, 2024). "For this reason, similar to our results with lymphomas, we anticipate that GZMB and GZMA will be the principal axes of cytotoxicity of BCMA CAR T cells targeting MM." (PMID 38307835, 2024).
malaria (3 papers, 2017 to 2026). Malaria is a serious and sometimes fatal disease caused by a parasite that commonly infects a certain type of mosquito which feeds on humans. "Similarly, in malaria these genes were either only modestly upregulated (GZMA and GZMB) or were downregulated (GZMH, GNLY and PRF1), compared to HS (P < .05)." (PMID 33793565, 2021).
Primary Immunodeficiency (3 papers, 2016 to 2019). "The top five canonical pathways contributing to down-regulated expression of genes related to EIF2, Primary Immunodeficiency, B cell development, Granzyme A and Regulation of eIF4 and p70S6K signaling pathways." (PMID 29764370, 2018).
prostate carcinoma (3 papers, 2022 to 2024). A carcinoma that arises from epithelial cells of the prostate gland. "Furthermore, CYThigh prostate cancer patients are more sensitive to ICIs due to the fact that high GZMA and PRF1 expression levels increase the number of CD8+ T cells and the expression of immune checkpoints, including PD-L1, compared to patients with low CYT levels." (PMID 38612436, 2024). "Finally, the disruption of the IL6R/STAT-3 axis in prostate cancer cells and the blocking of TIGIT on NK-92 were observed to increase the cytotoxicity of NK-92 cells against DU145 cells through an increase in sFasL, granzyme A, granzyme B, and granulysin." (PMID 35465350, 2022). "Likewise, we determined that using these treatments in combination with anti-TIGIT increases and maintains the expression of some factors such as NKp46 and secretion of granzyme A, granzyme B, perforin, and granulysin which may regulate cytotoxicity against DU145 prostate cancer cells." (PMID 35465350, 2022).
pulmonary tuberculosis (3 papers, 2021 to 2023). A bacterial infection that affects the lungs and is caused by Mycobacterium tuberculosis. "But, the expression of granzyme A, granzyme B, and perforin in patients with active pulmonary tuberculosis was higher than those in the healthy controls and patients with latent M. tuberculosis infection, and it decreased after curing." (PMID 37761328, 2023). "Increased abundance of granzyme A and granzyme B was observed in culture supernatants of NK cells isolated from pulmonary TB patients with cavity and cocultured with MTB protein lysates." (PMID 34646890, 2021).
asthma (2 papers, 2025). "A previous reports showed that increased expression of granzyme A in airway was associated with fatal asthma." (PMID 40410722, 2025). "SCFAs play a role in immune modulation, affecting T-cell differentiation and inflammation, processes linked to granzyme A signaling and Th2-driven asthma pathology." (PMID 40410722, 2025). "We identified the key biological processes influenced by ITIH4 in the OVA-induced asthma mice, by activating granzyme A signaling, iron uptake and transport, and the ESCRT." (PMID 40410722, 2025). "In mice with asthma, PFR-CK, which also inhibits plasma kallikrein, factor XIIa and granzyme A, was recently assessed (intraperitoneally every second day), displaying decreased airway eosinophil infiltration, reduced goblet cell hyperplasia, and improved lung function." (PMID 40607408, 2025). "The observed decrease in lymphocyte counts in BALF of ITIH4-treated OVA-induced asthma mouse may partially reflect reduced infiltration or activation of cytotoxic immune cells, particularly CD8+ T cells and Natural Killer (NK) cells, which are major sources of Granzyme A at sites of inflammation." (PMID 40410722, 2025).
atherosclerosis (2 papers, 2013 to 2023). A disease characterized by the build-up of fatty material and calcium deposition in the arterial wall resulting in partial or complete occlusion of the arterial lumen. "Atherosclerosis-specific C3 CD4+ T cells had slightly increased GZMA expression compared to PSA PBMCs and SF." (PMID 38665903, 2023). "However, given the well-documented role for IL-1β in inflammation and atherosclerosis combined with the known role for GzmA in the production of this cytokine and others, it is plausible that GzmA could be contributing to atherogenesisas well." (PMID 24205352, 2013). "In both PSA and atherosclerosis CD8+ C3 T cells, expression profiles displayed a similar phenotype with high expression of T cell effector genes—for example, CCL5, GZMH, GZMA, GZMK and NKG7." (PMID 38665903, 2023). "In the present study, we observed similar staining for GzmA in the plaques of ApoE KO, GzmB/ApoE DKO and Prf1/ApoE DKO mice.The exact role of GzmA and its influence on inflammation and plaque development in atherosclerosis remains to be investigated." (PMID 24205352, 2013).
Autoimmunity (2 papers, 2024). The occurrence of an immune reaction against the organism's own cells or tissues. "While in subacute/chronic disease stages an overt astrocytic damage was absent, the MHC class I upregulation along with CD8+/perforin+/granzyme A/B+ T cells attached to astrocytes suggest that cytotoxic T cell-mediated immune reaction is present in GFAP autoimmunity." (PMID 38310187, 2024).
bacterial sepsis (2 papers, 2021). "These cytokines have been involved in the physiopathology of bacterial sepsis 30-32 and the lower levels of these cytokines in GzmA deficient mice could explain their higher survival during E. coli sepsis." (PMID 34815792, 2021). "In conclusion, the role of GzmK in an in vivo mouse model of bacterial sepsis has been analysed for the first time and the biological relevance of GzmK and GzmA has been compared in bacterial sepsis." (PMID 34815792, 2021). "Here we aim to understand the role of GzmK in a mouse model of bacterial sepsis and compare it to the biological relevance of Granzyme A (GzmA)." (PMID 34815792, 2021). "It has been previously shown in other models that the presence of NK cells and GzmA is key for bacterial sepsis 14 and endotoxicosis." (PMID 34815792, 2021). "All these data suggest that GzmA plays an important role in bacterial sepsis." (PMID 34815792, 2021).
breast tumor (2 papers, 2017 to 2024). "To identify which bacterial taxa within the breast tumor microbiome are associated with TILs, we quantified the abundance of CD8+ and FoxP3+ TILs and retrieved expression levels of genes indicative of CD8+ T cell activation from our prior data, including GZMA/B/K and IFNG." (PMID 39554133, 2024). "Finally, lower levels of several pro-inflammatory cytokines (IL1B, IL10, IL12, IL6, IL8, TNF), NK cell metagenes (NCR1, XCL1), cytolytic enzymes (GZMA, GZMB, PRF) and type I IFN-induced genes were also observed in IL-1R8 high breast tumors." (PMID 28533483, 2017).
dengue (2 papers, 2017 to 2022). "Plasma levels of GzmA were significantly elevated in patients with dengue fever and cytomegalovirus infection, in chikungunya virus (CHIKV) patients, and in patients with respiratory syncytial virus infection." (PMID 36490282, 2022).
E. coli infection (2 papers, 2017 to 2021). "For this purpose, we used a murine model of E. coli abdominal infection in WT mice and mice deficient in gzmA and/or gzmB." (PMID 28694562, 2017). "Curiously, in blood, the percentage of NK cells expressing gzmA and gzmB increased after E. coli infection, suggestive of differential responses at the primary site of infection and systemically." (PMID 28694562, 2017). "The present study is the first, to our knowledge, showing the pattern of intracellular expression of gzmA and gzmB by different lymphocyte populations before and after induction of E. coli infection." (PMID 28694562, 2017). "Next, we analysed the role of GzmA and GzmK in the control of E. coli infection." (PMID 34815792, 2021). "We have found that similarly to GzmA, GzmK did not play an important role in the control of E. coli infection." (PMID 34815792, 2021). "In addition, it has been observed that neither GzmA nor GzmK are involved in the control of E. coli infection." (PMID 34815792, 2021).
endotoxemia (2 papers, 2020 to 2021). "Increased levels of GzmA and GzmB have been found in patients with severe gram negative bacterial infections as well as in healthy volunteers with an experimental endotoxemia with lipopolysaccharide (LPS)." (PMID 32655547, 2020).
graft versus host disease (2 papers, 2020 to 2025). An immune system disorder that occurs after allogeneic hematopoietic stem cell transplant and is a reaction of donor immune cells against host tissues. "A subset of granzyme A–producing CD4+ T cells accumulate in the intestines of mice and mediate the development of graft-versus-host disease after hematopoietic cell transplantation." (PMID 32809971, 2020).
head and neck squamous cell carcinoma (2 papers, 2023 to 2025). A squamous cell carcinoma that arises from any of the following anatomic sites: lip and oral cavity, nasal cavity, paranasal sinuses, pharynx, larynx, and salivary glands. "A study focusing on AI and radiomic analyses examined CT radiomic models developed to non-invasively predict granzyme A in head and neck squamous cell carcinoma and machine learning models for external auditory canal CT scans to evaluate the feasibility of endoscopic ear surgery." (PMID 40019544, 2025). "Our data revealed a strong positive correlation between the expression of CCR5, GZMA, IDO1, and PRF1 and CNV in both lung squamous cell carcinoma (LUSC) and head and neck squamous cell carcinoma (HNSC)." (PMID 37646041, 2023).
intestinal infection (2 papers, 2024 to 2025). "Granzyme A showed protective, antibacterial effects in the context of intestinal infections, and its increased secretion in IBD tissue slices may be related to increased exposure to intestinal pathogens due to intestinal epithelial barrier damage." (PMID 40705352, 2025). "Since IEL are the major cell type expressing GzmA and GzmB constitutively in the mouse, we could use GzmA/B dKO to address the function of IEL-derived Gzms in intestinal infection." (PMID 39137883, 2024).
kidney cancer (2 papers, 2022 to 2025). Primary or metastatic malignant neoplasm involving the kidney. "Notably, GZMA showed high positive correlations with kidney cancer in the context of ICB therapy, suggesting its potential as a predictive biomarker for therapeutic outcomes." (PMID 40002821, 2025). "However, high expression of cytolytic markers, GZMA or IFNG tend to suggest a good prognosis in blood and kidney cancers, respectively." (PMID 35197510, 2022).
metastatic tumors (2 papers, 2021). "GZMA and PRF1 were tightly co-expressed across both primary and metastatic tumors (Spearman rank correlation, rho ~ 0.9)." (PMID 33779796, 2021). "Beyond the infiltration of the cells, CTL activity (geometric mean of perforin and granzyme A expression) is not noticeably different between the primary and the recurrent/metastatic tumors." (PMID 33796222, 2021).
multiple sclerosis (2 papers, 2023 to 2024). A progressive autoimmune disorder affecting the central nervous system resulting in demyelination. "We observed a decrease in plasma Granzyme A, a marker of T cell and NK cell degranulation, which was specific to multiple sclerosis." (PMID 38282238, 2024). "Finally, astrocyte cluster 8 (MMP7, SERPINA3, GZMA, and CLIC1) and microglial cluster 2 (DSG2 and TNFRSF25) were elevated in multiple sclerosis patients and suggested the pathogenic role of these biomarkers during multiple sclerosis progression." (PMID 37468977, 2023).
myocarditis (2 papers, 2018 to 2025). Myocarditis is a condition that is characterized by inflammation of the heart muscle (myocardium). "TCR sequencing revealed expansions of CD8 GZMK + GZMA + and CD8 PRF1 + GZMA + T cells in myocarditis patients, along with increased activation markers CD69 and KLRG1, supporting the idea that specific cytotoxic CD8 T cell groups promote inflammation." (PMID 41510228, 2025). "Importantly, reversal of susceptibility to virus‐induced myocarditis by ONX 0914 was reflected by detection of additional signs of reduced immune‐mediated injury such as significantly decreased expression levels of the T‐cell effector molecules granzyme A, perforin‐1, and IFN‐γ in heart tissue." (PMID 29295868, 2018).
parasitemia (2 papers, 2015 to 2025). "Interestingly, it has been shown that Granzyme A knockout mice are more susceptible to infection by T. cruzi, suggesting a role for this molecule in control of parasitemia." (PMID 26147698, 2015).
Pleural effusion (2 papers, 2025). The presence of an excessive amount of fluid in the pleural cavity. "In liver metastasis BL T cells, granzyme family genes (GZMA, GZMH, and GNLY) were enriched, while pleural effusion BL T cells showed increased TFF3, AGR2, MGP, and MIF expression." (PMID 39955556, 2025). "Analysis of DEGs in Cycling GZMA and GZMA CD4 T cells from pleural effusion of HP and LCP revealed that seven transcription factors (MLLT3, KLF12, FOXP1, NFKB1, ZEB2, TOX, JAZF1) were upregulated in both cycling GZMA CD4 and GZMA CD4 cells in MPE of LCP." (PMID 40959273, 2025). "Compared to GZMA CD4 T cells in pleural effusion without tumors, those in MPE of LCP—whether non-proliferative or cycling GZMA CD4 T cells—exhibited suppressed cytotoxic function and reduced GZMA expression." (PMID 40959273, 2025).
pneumonia (2 papers, 2017 to 2021). An acute, acute and chronic, or chronic inflammation focally or diffusely affecting the lung parenchyma, caused by an infection in one or both of the lungs (by bacteria, viruses, fungi, or mycoplasma.). "This differs from our previous findings in a murine model of pneumonia, where the proportion of gzmA+ NK cells at the primary site of infection (the lungs) remained stable until late pneumosepsis, when there was a strong fall, while the MFI decreased in time." (PMID 28694562, 2017).
preeclampsia (2 papers, 2020 to 2021). Preeclampsia is a hypertensive disorder of pregnancy that is characterized by new-onset hypertension with proteinuria presenting after 20 weeks of gestation, and depending on mild or severe forms may initially present with severe headache, visual disturbances, and hyperreflexia. "Some genes identified in our GHT group have already been related to a preeclampsia-like phenotype, such as GZMA, METTL7B and DYSF43." (PMID 32296081, 2020).